INS (insulin)
Diseases named in the same sentence as INS in open-access papers (continued):
Sharing a sentence is not in itself a finding about the gene and the disease.
diabetes (continued). "Young patients with lower diabetes durationand absence of preoperative insulin therapy, showed that these data are significantpredictors of remission, regardless of the percentage of weight loss." (PMID 26537267, 2015). "About one-third (36 %) of the respondents manage the diabetes also of their patients who are treated with insulin; yet, 60 % reported lacking knowledge about nutritional issues." (PMID 25877332, 2015). "Her diabetes was well controlled with an insulin pump, and she did not take any additional medications." (PMID 26620704, 2015). "Hyperinsulinemia was also prevalent in T2DM population and insulin might influence thyrotropin releasing hormone (TRH) and TSH when modulating glycemic status, thus, diabetics might have higher TSH." (PMID 26270348, 2015). "Insulin and C-peptide levels were not significantly changed in the diseases groups as compared to control subjects, except diabetes with coronary artery diseases groups." (PMID 25894234, 2015). "Parallels are seen in systems medicine where serial analyses of the pulsatile secretion of insulin (rather than fasting insulin) was found to be an early feature of diabetes rather than a single value." (PMID 26303914, 2015). "Of the 320 respondents, 33 (10.3%) had Type 1 diabetes, 107 (33.4%) had Type 2 diabetes and were taking insulin, and 180 (56.3%) had Type 2 diabetes and were on oral agents (but not insulin) or controlled their diabetes with lifestyle interventions alone." (PMID 26126421, 2015). "In insulin-dependent tissues, such as adipose tissue and muscle, the phosphatidylinositol 3-kinase (PI3K)/Akt signaling was crucial for the metabolic effects of insulin, and this pathway was generally affected in individuals with the MetS and diabetes." (PMID 25774226, 2015). "Among patients with overt diabetes, 28 patients did not take any drug and the rest of them took oral diabetes drugs and insulin." (PMID 26185747, 2015). "By contrast, it is only when blood glucose is chronically elevated over many weeks and months, due to a sustained lack of insulin, that the complications of diabetes are produced." (PMID 25982967, 2015). "In the subgroup of patients without diabetes, differentials of HbA1c and insulin in the ICO group were less than those in the GLU group (HbA1c: P < 0.001; insulin: P = 0.017)." (PMID 26788499, 2015). "Refractory hypoglycemia was identified in two patients with no history of insulin use or diabetes mellitus." (PMID 26218286, 2015). "Uncontrolled studies examining the effect of CPAP on glucose tolerance and insulin sensitivity in OSA patients with or without diabetes have yielded mixed results, leading to no clear conclusion." (PMID 25834642, 2015). "Baseline diagnosis of diabetes was not available; however, baseline usage of both oral hypoglycaemic agents (9.3% versus 15.1%, p<0.001) and insulin (2.6% versus 3.7%, p = 0.005) was less common among the control group." (PMID 25815472, 2015). "Diabetic mice were maintained without insulin supplementation to allow for the progression of severe diabetes mellitus and the appearance of its complications." (PMID 26167475, 2015). "They found no significant changes in dimensions of the Diabetes Self-Care Inventory and the effect sizes varied (adherence d=0.11, blood glucose regulation d=0, insulin and food regulation d=0.12, and emergency preparedness d=0)." (PMID 26701961, 2015). "Our ADMSCs therapy decreased blood glucose levels, improved β-cell mass and insulin production but did not reverse the diabetes completely." (PMID 25884215, 2015). "In contrast, serum insulin measurement is not used as often, despite the fact that it can identify insulin-resistant subjects, which is a strong marker of future diabetes." (PMID 26241903, 2015). "Transplantation of cadaveric pancreases began to flourish in 1966, allowing people with diabetes to live without insulin injections." (PMID 26294917, 2015).
diabetes (continued). "Insulin dependent glucose transporters in diabetes are not able to carry required amount of glucose into the cells due to lack of insulin." (PMID 27275196, 2015). "This is because glucose uptake in peripheral nerves is not dependent on insulin and, high blood glucose levels in diabetes thus leads to high nerve glucose concentrations and this stimulates the polyol pathway." (PMID 26435536, 2015). "However, patients with diabetes and declining cognitive function may present with difficulties in managing self-care, including failure to effectively administer their medications such as oral tablets and insulin, monitoring, adherence to diet and exercise regimes." (PMID 26193295, 2015). "The World Health Organisation (WHO) defines diabetes as a chronic metabolic disease that occurs either when the pancreas does not produce enough insulin or when the body cannot effectively use the insulin it produces." (PMID 26258111, 2015). "It is worth mentioning that, at the time of enrollment of the diabetes cohort, insulin analogues were not yet available in Taiwan." (PMID 26171401, 2015). "Among the 85 studies that evaluated insulin, 59 focused on type 2 diabetes whereas the remaining studies did not specify diabetes type." (PMID 26076034, 2015). "Despite these findings, data on randomized controlled trials involving metformin and insulin in the management of Type 2 Diabetes Mellitus (T2DM) in pregnancy and GDM are lacking in the indigenous African population." (PMID 25945500, 2015). "As typically observed in previous studies comparing patients with and without DR, the patients with this condition had longer diabetes duration and were more likely to receive insulin treatment and antiplatelet agents." (PMID 25856787, 2015). "Apps such as Insulin Calculator, Bolus Calc, Insulin Dose Calculator Pro, and Diabetes Personal Calculator for non-pump users are available to help patients in insulin dosing." (PMID 28702234, 2015). "The majority of people with diabetes do not use insulin pumps due to cost, lack of insurance coverage, or other unrelated issues." (PMID 28702234, 2015). "In our study, type of medication of diabetes was classified to three categories; patients without medication, patients using insulin, and patients treated with oral anti-diabetic agents." (PMID 27617234, 2015). "As the major insulin-degrading protease, IDE is a candidate drug target in diabetes." (PMID 26394692, 2015). "Plasma leptin levels are positively correlated with female sex, BMI, and age but not with diabetes duration, HbA1c, or total insulin dose per kilogram." (PMID 26273677, 2015). "Regarding medication, only one of the clinics had a supply of oral medication for diabetes and none had insulin." (PMID 26245609, 2015). "The type of diabetes was not stated in this very small study but as the mean age at diagnosis was 31.6 years and 80 % were receiving insulin therapy, most drivers presumably had T1DM." (PMID 28702227, 2015). "Of the 128 diabetes patients not treated with metformin 67 (27.8%) were treated with diet alone, 35 (14.5%) with sulfonylurea alone, 23 (9.5%) with insulin alone and 1 (0.4%) with sulfonylurea and dipeptidyl peptidase-4 inhibitor (sitaglipin)." (PMID 26074965, 2015). "Type 1 DM is juvenile diabetes and is called as insulin dependent diabetes mellitus (IDDM) in which the pancreas fails to produce insulin due to autoimmune beta-cell destruction." (PMID 26273663, 2015). "The majority of driving licensing authorities in developed countries make a distinction between people with diabetes who require insulin therapy to treat their diabetes and those who do not." (PMID 28702227, 2015). "The aim of this study was to evaluate the effects of insulin on intestinal mucosal GU before and after bariatric surgery in individuals with and without diabetes." (PMID 25631620, 2015).
diabetes (continued). "Fifteen percent of respondents reported not knowing their diabetes status and fewer than half of self-reported type I diabetics reported using insulin." (PMID 26307533, 2015). "This phenotype is interesting in light of the fact that obesity and insulin resistance, which often correlate in humans, can be uncoupled, with 20% of obese people displaying a ‘healthy obese’ phenotype with good insulin sensitivity and no diabetes." (PMID 26440364, 2015). "Diabetes mellitus (DM) develops as a result of an actual or functional lack of insulin and it is a chronic condition that progresses to impairment in the patient’s carbohydrate, protein and lipid metabolism." (PMID 26316432, 2015). "In conclusion, our study suggested that chronic smoking impaired insulin secretion and probably brought about insulin resistance in Chinese men without diabetes." (PMID 26236748, 2015). "Diabetes is a metabolic disorder characterized by the inability of the pancreas to produce enough insulin or the body's lack of ability to effectively use insulin." (PMID 25707942, 2015). "A study based on 508 Chinese individuals with diabetes mellitus also indicated that that the fasting glucose/ insulin ratio is not a reliable index of insulin sensitivity." (PMID 25635876, 2015). "For example, partial disinvestment has been implemented in Ontario for routine vitamin B12 testing, routine ferritin testing, and daily use of diabetes test strips by people with diabetes who do not take insulin." (PMID 26290289, 2015). "In the current context of improving diabetes care, patients with T1D selected to participate presented an adequate metabolic control and BMI, and no developed chronic complications related to diabetes or other drug except insulin." (PMID 26317989, 2015). "In general, diabetes mellitus is a group of metabolic diseases in which the pancreas is not able to produce insulin, insulin production is not sufficient or cells cannot effectively use this hormone." (PMID 25786107, 2015). "LADA is usually defined as GAD antibody-positive diabetes with onset greater than 35 years of age and no insulin requirement during the first 6 months after diagnosis." (PMID 25774817, 2015). "We consider dividing a diabetes web portal immediately after the entrance in two parts: one for patients who are injecting insulin and another for patients who do not." (PMID 26086272, 2015). "Method of treatment for pre-existing diabetes (not in table): 58.5% with an insulin pump; 39.6% via insulin by injection, 1 adolescent patient on metformin and insulin." (PMID 25889476, 2015). "When the pancreas does not produce sufficient insulin or the body is unable to utilize the insulin, diabetes mellitus is developed." (PMID 25950001, 2015). "On the contrary, insulin restriction, as diabetes-specific purging behavior, has not been considered when estimating the prevalences of EDs; however, detailed results regarding this behavior have been previously published." (PMID 26121155, 2015). "The absolute or relative lack of insulin is the key factor in the pathogenesis of diabetes mellitus." (PMID 26426397, 2015). "Mean duration of diabetes was 13 years, and 20 % of the patients were on insulin only, with another 23 % on both insulin and noninsulin agents." (PMID 25523512, 2015). "The use of Insulin for the treatment of diabetes also did not correlate significantly to functional maturation (P = 0.839)." (PMID 25768440, 2015). "The improvement in insulin sensitivity with TNFi therapy observed in RA does not echo the findings in other disease conditions such as diabetes mellitus and inflammatory bowel disease." (PMID 26110878, 2015). "In people without diabetes, the concurrent stimulation of glucagon counters the effects of protein-induced insulin release (whilst still allowing insulin to transport amino acids into the cells), and thus, there is minimal impact on postprandial glycaemia." (PMID 26202844, 2015).
diabetes (continued). "The diabetic animals displayed impaired glucose metabolism, without wasting or need for exogenous insulin treatment, suggesting a mild condition of diabetes with no body weight differences observed between diabetic and non-diabetic obese animals." (PMID 26394837, 2015). "Two patients were treated with insulin due to diabetes mellitus, whereas none received oral anti-diabetic agents." (PMID 25908211, 2015). "This form of diabetes is characterized by direct destruction of the insulin producing cells due to several reasons (e.g. toxic) and not by altered insulin-sensitivity and production." (PMID 26334523, 2015). "Therefore, the ability to non-invasively evaluate insulin sensitivity index (ISI0,120) for diagnosis of pre-diabetes and type 2 diabetes has a substantial clinical significance." (PMID 26148706, 2015). "Men with diabetes had 3.8-fold increase in CACS prevalence compared with insulin sensitive men without diabetes." (PMID 27734010, 2015). "Some studies with experimental diabetes, including those with high doses of MLT, showed a normalization of blood glucose levels; however, this effect of MLT has been clearly reported for obese rodents in which there is an improvement in insulin sensitivity." (PMID 26064423, 2015). "The proportion of those with diabetes and/or treatment with insulin was not significantly higher in those who self-reported a history of RTAs in the preceding 12 months." (PMID 28702227, 2015). "Subjects categorised as pre-diabetic using HbA1c had lower BMI and WC levels, lower triglyceride and insulin concentrations, higher HDL-C levels, were less hypertensive, and a greater proportion were female when compared to individuals with pre-diabetes defined by FPG." (PMID 26266799, 2015). "In this study, it was determined that patients with diabetes lacked knowledge about the following issues: insulin dosage adjustment during illness, suitability of food choices, frequency of need for ophthalmology review and foot care." (PMID 26005688, 2015). "The results from our investigation suggest that neither of the two types of insulin investigated provided significantly greater reduction in diabetes-related emotional distress when starting insulin therapy." (PMID 26055391, 2015). "Two patients died of refractory hypoglycemia and were free of diabetes with no history of insulin use, but they were emaciated." (PMID 26218286, 2015). "In bivariate analysis, age, diabetes duration, being under insulin treatment, blood glucose level, having non-communicable diseases were significantly associated with DR." (PMID 25925666, 2015). "The bivariate logistic regression showed that age, being overweight, diabetes duration, being under insulin treatment, blood glucose level, having non-communicable diseases (hypertension, renal and heart diseases) were significantly associated with DR." (PMID 25925666, 2015). "INS 120 significantly increased in people with prediabetes or diabetes compared with control, together with FPG and OGGT, indicating insulin resistance in people with prediabetes or diabetes." (PMID 25785633, 2015). "One patient was prescribed insulin Glargine (Lantus, Sanofi-Aventis), one patient was prescribed insulin Aspart (NovoLog, Novo Nordisk), and one patient did not report taking any medication for diabetes." (PMID 26581717, 2015). "In the current study, we hypothesized that 1) the major cardiac GLUT isoform, GLUT4, and the novel GLUT isoform, GLUT8, will be regulated by insulin in the atria and 2) GLUT translocation will be impaired during diabetes." (PMID 26720696, 2015). "Unfortunately, we did not have data to test the role of diabetes treatment on the mention of the disease (no treatment, only oral anti-diabetic drugs, insulin)." (PMID 26309427, 2015). "None of the patients without a recorded history of diabetes was treated with oral antidiabetics or insulin therapy." (PMID 25964053, 2015).
diabetes (continued). "Although the presence of established insulin therapy is collected at the time of admission, categorization of patients as type 1 or type 2 diabetes mellitus is not available." (PMID 26715333, 2015). "One study specifically showed that in T1D patients with pubertal compared to pre-pubertal onset, glycemic control was better and daily insulin doses were lower after 6 years of diabetes, irrespective of age-related factors." (PMID 26173476, 2015). "But although lack of insulin, and the consequent diabetes, receives much attention, an acute excess of insulin is far more damaging." (PMID 25982967, 2015). "The diagnosis can be made if there is evidence of adult-onset non-insulin-requiring diabetes (>30 years of age), positive circulating autoantibodies, and no need for insulin treatment during several months after diagnosis." (PMID 25834574, 2015). "Taken together, our data show that the increased betatrophin level in T2D subjects is not correlating with insulin production and its use as a diabetes treatment is questionable." (PMID 26289721, 2015). "One study, which directly compared isolated PRT to aerobic exercise in middle-aged type 2 adults with diabetes, found that PRT significantly improved 48-hour continuous glucose control, HbA1c, insulin sensitivity, and lipids, whereas aerobic exercise was ineffective." (PMID 26554457, 2015). "The UK Prospective Diabetes Study Group (UKPDS) demonstrated that there is an inexorable decline in β-cell function with time, whether with diet-control, insulin or sulfonylurea therapies." (PMID 25982967, 2015). "The Federal government in the United States does not impose any specific restrictions regarding driving for people with diabetes who are not treated with insulin." (PMID 28702227, 2015). "The onset of this type of diabetes is normally before 25 years and its treatment is independent of insulin." (PMID 26587547, 2015). "By demonstrating that intake of a low AGE diet improves insulin sensitivity and/or secretion, large scale interventions using low AGE diets could potentially become a mainstream strategy for diabetes prevention in overweight and obese individuals." (PMID 26223897, 2015). "Of additional interest is insulin even among CKD patients without manifest or overt diabetes mellitus." (PMID 26635963, 2015). "As an example, no valid information on diabetes type and prescribed daily insulin doses were available in the database." (PMID 25698911, 2015). "We studied the relationship between glycemic control defined by glucose serum concentrations and insulin resistance, beta2M and markers of inflammation in patients on renal replacement therapies with or/and without diabetes mellitus." (PMID 25922828, 2015). "Higher concentrations of Ca in diabetics and positive correlations with HOMA-IR and insulin levels may indicate a detrimental effect of this mineral on carbohydrate metabolism." (PMID 25867198, 2015). "Mice maintained on the LFD throughout the experiment exhibited predominantly small-sized pancreatic islets regardless of insulin therapy at onset of diabetes." (PMID 25633992, 2015). "Type 2 diabetes mellitus (T2DM), which is an epidemic globally, is also known as non-insulin-dependent diabetes mellitus, and it is characterized by insulin resistance and impaired insulin secretion due to beta-cell dysfunction." (PMID 26715102, 2015). "As disease progressed to overt diabetes, ZDSD rats demonstrated elevated glucose levels, abnormal oral glucose tolerance, increases in HbA1c levels, reductions in body weight, increased insulin resistance with decreasing insulin levels, and dyslipidemia." (PMID 25961053, 2015). "Diabetes incidence after DPPHR ranges within 8–21% and some patients show significant improvement in glucose metabolism and appears to be related to preservation of insulin and pancreatic polypeptide secretive function." (PMID 26380142, 2015).